SPATA3 (spermatogenesis associated 3)
Synonyms: TSARG1
Tractability: No criterion of Open Targets' tractability assessment is met for any kind of drug.
Gene: Protein-coding gene on chromosome 2 (230,990,324 to 231,025,055, forward strand). Ensembl gene ENSG00000173699.
Subcellular location: Cell projection, cilium, flagellum
Gene Ontology:
Cellular component: sperm flagellum; motile cilium
Genetic constraint (gnomAD): Loss-of-function variants: 8 observed, 5.45 expected, observed/expected ratio (o/e) 1.47, 90% interval 0.81 to 1.93. That is too few expected variants to judge how well the gene tolerates losing a copy. Missense variants: 143 observed, 113.94 expected, observed/expected ratio (o/e) 1.26, 90% interval 1.1 to 1.44. Synonymous variants: 42 observed, 40.25 expected, observed/expected ratio (o/e) 1.04, 90% interval 0.81 to 1.35.
Homologues: Orthologues: chimpanzee SPATA3 (96% identical), macaque SPATA3 (95% identical), rabbit SPATA3 (63% identical), pig SPATA3 (61% identical), dog SPATA3 (60% identical), guinea pig SPATA3 (55% identical), rat Spata3 (43% identical), mouse Spata3 (42% identical).
Diseases named in the same sentence as SPATA3 in open-access papers:
SPATA3 is named in the same sentence as 7 diseases in open-access papers, as found by Europe PMC text mining. Sharing a sentence is not in itself a finding about the gene and the disease. The quoted sentences say what the papers report.
Globozoospermia (2 papers, 2019 to 2021). Any structural anomaly of the acrosome resulting in a round sperm head. "On the human side, SPATA3 and other potential candidate genes from the QTL region should be screened in infertile/hypofertile patients with signs reminiscent of globozoospermia." (PMID 33669425, 2021). "The Spata3 KO, though modestly affecting sperm capacities, is therefore an incomplete reproduction of the Rc3 IRCS mouse line, that was considered as a model of partial globozoospermia." (PMID 33669425, 2021).
infertile (2 papers, 2021 to 2022). "SPATA3 has been demonstrated to be the most significantly down-regulated gene in the testes of infertile patients and to play a key role in mouse spermatogonia development." (PMID 36330159, 2022). "SPATA3 has been shown to be the most significantly downregulated gene in the testis of infertile patients." (PMID 34438721, 2021).
male infertility (2 papers, 2023). The inability of the male to effect fertilization of an ovum after a specified period of unprotected intercourse. "The male infertility-related variants identified in SPATA3, TTC21A, TERB1, HYDIN, and CCDC155 can be considered additional examples." (PMID 37644014, 2023). "SPATA3 interacts with KLHL10, which is expressed exclusively in spermatids, and its inactivation leads to the disruption of spermiogenesis and complete male infertility in mice." (PMID 36899892, 2023).
Obesity (1 paper, 2025). Accumulation of substantial excess body fat. "Additionally, Piwil1, Spata3, and Trib1 have previously been associated with obesity and its complications." (PMID 40944384, 2025).
SPATA3 also shares sentences with these, for which no sentence is quoted: Fanconi anemia (1 paper); melanoma (1); prostate carcinoma (1).